ABO (ABO, alpha 1-3-N-acetylgalactosaminyltransferase and alpha 1-3-galactosyltransferase)
Diseases named in the same sentence as ABO in open-access papers (continued):
Sharing a sentence is not in itself a finding about the gene and the disease.
thrombosis (16 papers, 2016 to 2025). "The ABO locus, genetically predicted blood group A, and higher genetic propensity for venous thrombosis are more strongly associated with EOS than with LOS, supporting a stronger role of prothrombotic factors in EOS." (PMID 36240095, 2022). "As ABO becomes methylated the level of F8 in the blood raises and this consequently increases the risk of thrombosis (B = 0.01, P = 7.57e−34) and the risk for CAD (B = 0.06, P = 1.25e−08)." (PMID 33574266, 2021). "The aim of our present study was to determine the frequencies of thrombosis related ABO, F5, MTHFR, and FGG gene polymorphisms in morbidly obese patients and compare them with the group of nonobese individuals." (PMID 27999448, 2016). "Certain blood types are known to carry a higher risk of thrombosis, and genetic variations in ABO may contribute to this predisposition." (PMID 40375318, 2025). "The results demonstrated that two SNPs in ABO gene, rs495828 and rs2519093, had strong correlation with thrombosis in PNH, the minor alleles of the two SNPs were associated with 5.95 and 6.3 fold increase risk of thrombus formation, compared with major alleles." (PMID 29190926, 2017). "Among the rest fifteen SNPs detected, the rs495828 of ABO gene was significant relevant to an increased risk of thrombosis in PNH patients, as shown by the dominant model (GT+TT vs. GG: OR 5.95, 95% CI 1.90-18.65, P=0.002) and allele model (T vs. G: OR 3.52, 95%CI 1.57-7.90, P=0.003)." (PMID 29190926, 2017). "A GWAS study identified ABO rs505922 as a risk factor for venous thrombosis." (PMID 27999448, 2016). "Thus, the association of ABO and vWF with cardiovascular disease is mainly seen among those with an atherosclerotic event, including thrombosis, such as MI or ischemic stroke, whereas other factors influence the early and ongoing progression of atherosclerosis." (PMID 39844181, 2025). "Variants at the ABO locus (rs495828, rs505922) associated with the largest number of phenotypes (nrs495828 = 53 and nrs505922 = 59); strongest association with venous embolism, odds ratio (ORrs495828 1.33 (p = 1.32 x 10−199), and thrombosis ORrs505922 1.33, p = 2.2 x10-265." (PMID 35482673, 2022). "Variants at the ABO locus (rs495828, rs505922) associated with the largest number of phenotypes (nrs495828=53 and nrs505922=59); strongest association with venous embolism, odds ratio (ORrs495828 1.33 (p=1.32 × 10−199), and thrombosis ORrs505922 1.33, p=2.2 × 10−265." (PMID 34642702, 2021). "Genomic DNA was extracted and was genotyped for the 5-SNPs Genetic risk score (GRS), previously validated for first venous thrombosis (FVL rs6025, PTM rs1799963, ABO rs8176719, FGG rs2066865 and FXI rs2036914)." (PMID 34200207, 2021). "Haplotype analysis displayed that the combination of twp SNPs could correlation with the thrombosis risk in PNH, an increased risk of thrombosis was observed for the haplotype containing the rs495828 T and the rs2519093 T alleles of the ABO gene in PNH patients." (PMID 29190926, 2017).
venous thromboembolism (16 papers, 2012 to 2025). Occlusion of the lumen of a vein by a thrombus that has migrated from a distal site via the blood stream. "Three of the intron variants have an impact on ABO protein synthesis, which influences the red cell count and is associated with metabolic diseases such as diabetes and venous thromboembolism (VTE)." (PMID 36859360, 2023). "mGWAS-Explorer provided insights into these possible mechanisms, which identified associations of ABO variants with levels and the ratios of fibrinogen A-α peptides (e.g., ADpSGEGDFXAEGGGVR) and venous thromboembolism." (PMID 35736459, 2022). "Thus, using the random-effects model, the relationship between the ABO blood group and the risk of venous thromboembolism in individuals with Factor V Leiden was investigated." (PMID 36010287, 2022). "Moreover, ABO gene polymorphisms are independently associated with cardiovascular disease, angiotensin converting enzyme activity, red blood cell indices and venous thromboembolism, all of which have been reported to serve a pivotal role in the pathogenesis of severe COVID-19 infection." (PMID 34290882, 2021). "rs2519093, rs495828, rs8176719 in ABO gene has been demonstrated to be related with venous thromboembolism by Heit and colleagues, but it is the first time to be shown in patients with PNH." (PMID 29190926, 2017). "ABO is identified as the most significant locus in a GWAS of venous thromboembolism." (PMID 41322025, 2025).
diabetes (15 papers, 2012 to 2024). "HNF4G and PDX1 may induce PDAC-associated diabetes, whereas ABO may induce the causative effect of VTE on PDAC." (PMID 39002386, 2024). "Eleven ST3GAL4 SNPs were significantly associated with the plasma level of VWF antigen before adjustments for age, BMI, hypertension, diabetes, ever-smoking status, and ABO." (PMID 27584569, 2016). "Among the 14 ST3GAL4 SNPs found in ARIC GWAS, the intronic rs2186717, rs7928391, and rs11220465 were associated with VWF levels and with FVIII activity after adjustment for age, BMI, hypertension, diabetes, ever-smoking status, and ABO." (PMID 27584569, 2016). "Also, ABO rs657152 correlates with an increased likelihood of hypercholesterolemia, diabetes, and heart failure as well as decreased odds of gastrointestinal diseases such as duodenal ulcer and duodenitis." (PMID 36419842, 2022).
type 2 diabetes (14 papers, 2012 to 2025). "Similarly, children with the type 2 diabetes risk allele rs529565-C in ABO had higher MASP1 levels in our data, consistent with elevated MASP1 levels in patients with type 2 diabetes." (PMID 39972214, 2025). "We used the ‘insulin secretion’ pPS of variants in eight genes associated with type 2 diabetes risk due to poor beta cell function: MTNR1B, HNF1A, GCK, TCF7L2, TMEM258, ADCY5, SLC3OA8 and ABO." (PMID 35247066, 2022). "Other GWAS studies also identified ABO as a locus for low-density lipoprotein (LDL-C), type-2 diabetes, inflammatory risk biomarkers E-selectin, P-selectin, and sol-ICAM1." (PMID 24475106, 2014).
breast carcinoma (11 papers, 1986 to 2025). "Among those GWAS significant SNPs for breast cancer, previous studies show that one SNP in the ABO gene is associated with thyroid function." (PMID 32838791, 2020). "The primary objective of our study is to summarize and analyze available evidence about the relationship between the ABO blood group system and breast cancer." (PMID 40353794, 2025). "Our online search identified 4 SNPs — rs1800562 in HFE, rs174577 in FADS2, rs651007 in ABO and rs4921915 in NAT2 — related to LDL-C, TCHO, and/or TG levels, which have been reported to influence breast cancer risk." (PMID 34229617, 2021). "The ABO(H) and Y antigen status of epithelial cells from 45 breast carcinomas, 14 benign breast lesions and 7 normal breasts have been assessed using an indirect immunoperoxidase histochemical assay and a series of blood group specific monoclonal antibodies." (PMID 3516191, 1986). "DEP has sufficient resolution to distinguish similar populations of cells, including stimulated vs nonstimulated Jurkat cells, subpopulations of human leukocytes, red blood cells on the basis of ABO type, and breast cancer cells transfected with the neu oncogene." (PMID 31737160, 2019). "Based on these data, ABO/Rh blood group could be used as a prognostic factor in breast cancer patients." (PMID 19689811, 2009).
Hyperbilirubinemia (11 papers, 2012 to 2025). An increased amount of bilirubin in the blood. "The major risk factors associated with hyperbilirubinemia in pretermbabies in this study were found to be ABO incompatibility, sepsis, and Rhisoimmunization." (PMID 33457466, 2020). "In the current study, the cause of indirect hyperbilirubinemia was ABO incompatibility in 335 (42.5%) cases, Rh incompatibility in 64 (8.1%) cases, combined ABO and Rh incompatibility in 27 (3.4%) cases, sepsis in 55 (7%) cases and cephalhematoma in 4 (0.5%) cases." (PMID 37545932, 2023). "We suspected that ABO HDNs that carried the gene variant for Gilbert’s syndrome may have a higher risk of developing severe hyperbilirubinemia." (PMID 34074250, 2021). "This association may caution clinicians to assess UGT1A1 variations for neonates with ABO hemolysis, and may aid in the identification of high-risk population, which is important for management and intervention of hazardous hyperbilirubinemia." (PMID 34074250, 2021). "The logistic regression analysis identified preterm birth ( < 37 weeks), ABO hemolysis, G6PD deficiency, and elevated TSB levels at discharge as independent risk factors significantly associated with readmission for neonatal hyperbilirubinemia." (PMID 40168352, 2025). "UGT1A1 variant in coding region is actively involved in the pathogenesis of ABO hemolysis related neonatal hyperbilirubinemia." (PMID 34074250, 2021). "Neonatally, she had a prolonged requirement of phototherapy for indirect hyperbilirubinemia that started on the second day of life; slightly elevated was also conjugated bilirubin, which was attributed to ABO alloimmunization." (PMID 34177811, 2021). "Our data demonstrate that G211 mutation in the UGT1A1 gene, ABO incompatibility, G6PD deficiency, and the SS genotype of the repeats in the promoter region of the HO-1 gene are risk factors for neonatal hyperbilirubinemia in Fujian, Southeastern China." (PMID 30298137, 2018). "Additional risk factors for hyperbilirubinemia were observed in eight or 23% G6PD deficient infants; including pre-term (n = 4), ABO or Rh incompatibility (n = 3), and preterm with sepsis (n = 1)." (PMID 22906047, 2012). "It has been suggested that the high incidence rate of hemolytic anemia, caused by ABO alloimmunization or glucose-6-phosphate dehydrogenase (G6PD) deficiency, may predispose these populations to neonatal hyperbilirubinemia." (PMID 34074250, 2021). "The most common underlying diagnosis was ABO isoimmunization, whereas no infant exposed to hazardous hyperbilirubinemia could be ascribed to Rh isoimmunization." (PMID 30901042, 2019). "Additionally, multivariate logistic regression analysis identified that the mutant genotype of rs4148323 in the UGT1A1 gene, ABO incompatibility, G6PD deficiency, and SS genotype at rs1805173 locus of the HO-1 gene were genetic risk factors of neonatal hyperbilirubinemia." (PMID 30298137, 2018). "In addition, UGT1A1 211G>A was found to mildly exacerbate the severity of hyperbilirubinemia induced by ABO/Rh incompatibility, although the effect is not statistically significant." (PMID 38274110, 2023).
ischemic stroke (11 papers, 2013 to 2025). A stroke disorder caused by obstruction of blood flow to the brain, due to thrombotic (local blood clot formation) or embolic (due to a blood clot or other material traveling from another site) event. "We also identified two common variants (MAF ~ 0.20 in European ancestry) in ABO that are in high linkage disequilibrium with each other and that have been previously associated with ischemic stroke." (PMID 36672803, 2022). "This deletion variant has previously associated with ischemic stroke and is in near-perfect linkage disequilibrium (LD) with rs635634, the lead ABO SNP associated with all ischemic stroke in MEGASTROKE." (PMID 36240095, 2022). "We selected four single nucleotide polymorphisms (rs579459, rs651007, rs514659 and rs529565) of the ABO gene and performed genotyping assays to assess the association with ischemic stroke and its subtypes." (PMID 27542834, 2016). "First, we selected four SNPs of the ABO gene which showed association with CAD or ischemic stroke in the European population." (PMID 27542834, 2016). "Against this background, in the present study we aimed to investigate the association between four SNPs (rs579459, rs651007, rs514659 and rs529565) of ABO gene and ischemic stroke susceptibility in the Chinese population." (PMID 27542834, 2016). "The ABO locus also showed association with cardioembolic ischemic stroke and has recently also been shown to reach genome-wide significance with all ischemic stroke [40•, 54]." (PMID 27796860, 2016). "Fewer studies have investigated the genetic association between ABO polymorphisms and ischemic stroke." (PMID 27542834, 2016). "Our study examined the association between four variants in the ABO gene and the risk of ischemic stroke and its subtypes, large-artery atherosclerosis (LAA) and small-vessel diseases (SVD) in the Chinese population." (PMID 27542834, 2016). "The future studies will be required to confirm the association between ABO gene and ischemic stroke and its subtypes by high density genotyping on SNPs of ABO gene." (PMID 27542834, 2016). "In the present study we aimed to investigate the association between ABO gene and ischemic stroke and its main subtypes in the Chinese population." (PMID 27542834, 2016). "Recent GWAS showed that three SNPs (rs505922, rs643434, and rs651007) of ABO gene were associated with ischemic stroke and its subtypes in the European population." (PMID 27542834, 2016). "Our results demonstrate that the association between ABO SNPs and ischemic stroke is limited to large-artery and cardioembolic stroke, but absent in small-vessel stroke." (PMID 23381943, 2013). "Genetic variant rs505922 in the ABO locus was found to be associated with ischemic stroke, and in particular the subtypes large-vessel and cardioembolic stroke, but not small-vessel disease." (PMID 23381943, 2013). "Therefore, prospective studies with a comparatively large sample size are required to confirm the association between ABO gene and ischemic stroke in the Chinese population and to characterize the functional role of ABO underlying ischemic stroke or LAA." (PMID 27542834, 2016). "However, there were no independent replication studies regarding the association between ABO gene and ischemic stroke in Chinese population." (PMID 27542834, 2016). "Hence, in our case–control study, we investigated the association of four polymorphisms in ABO gene with the risk of ischemic stroke and its main subtypes." (PMID 27542834, 2016). "However, fewer studies focus on the association between ABO gene and ischemic stroke." (PMID 27542834, 2016). "The ABO blood types of 9,542 ischaemic stroke (IS) patients were inferred using two ABO gene loci (c.261G > del; c.802G > A)." (PMID 38965603, 2024). "Taking all these considerations together, the ABO gene may be a promising candidate gene of ischemic stroke." (PMID 27542834, 2016).
ischemic stroke (continued). "Our findings indicated that genetic variations of ABO gene may contribute to susceptibility of LAA but not ischemic stroke and SVD in the Chinese population." (PMID 27542834, 2016). "However, there was no study reported the association between ABO gene and ischemic stroke in the Chinese population." (PMID 27542834, 2016).
thalassemia (10 papers, 2008 to 2025). An inherited blood disorder characterized by a decreased synthesis of one of the polypeptide chains that form hemoglobin. "Τhe International Collaboration for Transfusion Medicine Guidelines stresses that individuals with SCD or thalassemia should in most cases be transfused with ABO, Rh (D, C, E), and K matched RBCs to minimize the risk of alloimmunization." (PMID 40590912, 2025). "Evidence summary and rationale: As with Recommendation 1 for SCD patients, no study from the updated review specifically compared limited matching (ABO and RhD) to the RhD, RhCcEe, and K‐matched approach for thalassaemia patients." (PMID 39535318, 2025). "The ABO profiles of thalassemia patients wereB-33, A-19, O-11, and AB-3, with 63 Rh-D positives and 3 Rh-D negatives." (PMID 37822830, 2023). "Several haemoglobin genotypes and blood groups (e.g., HbSS, HbSC, HbAC, alpha-thalassaemia trait, ABO) are known to affect the invasion and/or growth rate of P. falciparum parasites." (PMID 37208733, 2023). "The contributions of the new loci tend to be greater than the established effects of ABO blood group (0.2%), α-thalassemia (0.3%), and G6PD (0.5%), making them enticing targets for further investigation, including functional studies." (PMID 25805752, 2015). "Recommendation 4: Patients with thalassaemia who do not have any known alloantibody(ies) should be transfused with ABO, RhD, RhCcEe, and K‐matched RBCs to reduce the risk of alloimmunisation and delayed HTRs (low quality of evidence, weak recommendation)." (PMID 39535318, 2025). "Red blood cell (RBC) antigen matching beyond ABO and RhD is commonly recommended for patients with sickle cell disease (SCD) and thalassaemia." (PMID 39535318, 2025). "Previous evidence‐based guidelines have provided recommendations for prophylactic RBC matching beyond ABO and RhD in patients with SCD and thalassaemia aimed at reducing risks of alloimmunisation." (PMID 39535318, 2025). "We recommend the use of extended phenotyping, including ABO, RH, Kell, Duffy, Kidd, and MNS blood group systems, in transfusion practice for patients with sickle cell disease and thalassemia in the Al-Ahsa Region." (PMID 37152479, 2023). "The guideline panel recommends that ABO, RhDCcEe, and K‐compatible RBCs are selected for individuals with SCD and thalassaemia, even in the absence of alloantibodies, and that RBCs which are antigen‐negative to already existing clinically significant antibodies are chosen." (PMID 39535318, 2025).
viral infection (10 papers, 2020 to 2024). "Accordingly, an association of ABO types with viral infections is in some cases documented or has been suggested." (PMID 35364749, 2022). "A well-known example is the ABO blood group system in humans and primates which is often discussed as a risk modifier for a variety of viral diseases." (PMID 35364749, 2022). "Viral infections and association with the ABO blood groups have been reported for influenza, picornaviruses, hepatitis B virus, norovirus, and HIV infection." (PMID 35096865, 2021). "The ABO blood typing and the ABO gene variant analysis have been a central component of the immune response in transplantation and transfusion medicine, but has also been of importance in the immune response and progression of viral infections." (PMID 35096865, 2021). "An association with ABO blood antigens has been observed in a cohort of Chinese patients, with the type A and 0 being respectively at highest and lowest risk to be infected, as previously been reported for other viral infections." (PMID 32933522, 2020). "In epithelial tissues and secretions, ABO expression is heavily dependent on the inheritance of the Secretor Se/FUT2 gene which can also be protective against viral infection." (PMID 34124710, 2021). "In addition, the AUC-ROC values for ABO rs657152 were 0.723, showing that host genetic factors play a role in viral infection mortality." (PMID 36419842, 2022). "We investigated secretor status because expression of ABO glycans on secreted proteins and non‐erythroid cells are controlled by a fucosyltransferase (FUT2), and inactivating FUT2 mutations result in a non‐secretor phenotype which protects against some viral infections." (PMID 34124710, 2021).